NEDD4 (NEDD4 E3 ubiquitin protein ligase)
Diseases named in the same sentence as NEDD4 in open-access papers (continued):
Sharing a sentence is not in itself a finding about the gene and the disease.
cancer (continued). "In light of these findings, NEDD4 overexpression in NSCLC has been suggested to be the primary factor in driving PTEN levels down in a large proportion of these cancers." (PMID 22536248, 2012). "NEDD4-1 overexpression inversely correlates with PTEN protein levels in these cancers." (PMID 40002221, 2025). "Emgering data shown NEDD4 promotes cancer progression through ubiquitination-depedent degradation." (PMID 39444619, 2024). "In NSCLC tumors, NEDD4 was upregulated and promoted cancer cell tumorigenesis and drug resistance." (PMID 39444619, 2024). "NEDD4 increases cancer stemness, FLRT2 abrogates the NEDD4-induced NSCLC progression." (PMID 39444619, 2024). "Additionally, NEDD4 is a proto-oncogene that downregulates PTEN expression, thereby impacting the PI3K/AKT/mTOR pathway that is implicated in multiple types of cancers." (PMID 39726707, 2024). "NEDD4-1 can positively regulate the phagophore nucleation via targeting Beclin-1 in cancer cells." (PMID 36918822, 2023). "Additionally, there is a need to search for chemical compounds with notable properties enabling them to activate tumor suppressor NEDD4 in cancer cell lines." (PMID 37568787, 2023). "Thus, the expression levels of RAS, AKT, and PTEN in NEDD4-knockdown cells have been controversial among cancer cell types." (PMID 36672488, 2023). "Although emerging evidence suggest that NEDD4 E3 ligase family members play critical roles in different aspects of tumor, no comprehensive analysis has been conducted to demonstrate the entire landscape of NEDD4 family members in all types of cancers." (PMID 37291499, 2023). "NEDD4 regulates PTEN levels in several types of human cancers." (PMID 37497216, 2023). "Recent studies have examined the role of NEDD4 in tumorigenesis amongst several types of cancer." (PMID 38097550, 2023). "Moreover, higher expression levels of KLF8, NEDD4 and NRF2 were noticed in the tumor tissues of mice inoculated with NEDD4-overexpressing T24 cancer cells." (PMID 37568787, 2023). "Regarding the versatility of NEDD4 E3 ubiquitin ligases in catalyzing both proteolytic and non-proteolytic ubiquitination of a wide range of target substrates, their role in defective autophagy in cancer cells can be concluded to be context-dependent." (PMID 36918822, 2023). "Moreover, AKT, a major effector enzyme that promotes metabolic reprogramming in cancer cells, is also a target of NEDD4." (PMID 37176148, 2023). "Pulmonary metastasis was found in mice injected with NEDD4-overexpressing cancer cells." (PMID 37568787, 2023). "Emerging evidence has started to highlight the oncogenic role of NEDD4-1 in cancer progression." (PMID 37568787, 2023). "The NEDD4 mRNA expression levels in cancer tissues were measured." (PMID 36672488, 2023). "However, as explained in the last sections, each member of the NEDD4 E3 ligase family indicates multi-faced roles, pro- or anti-autophagic and tumor-suppressor or –promotor, in various types of cancer cells." (PMID 36918822, 2023). "The search was performed using the terms [(autophagy) AND (E3 ubiquitin ligase) AND (“HECT” OR “homologous to the E6AP carboxyl terminus” OR “NEDD4” OR “Neural precursor cell expressed developmentally downregulated protein 4”) AND (“cancer” OR “tumor”)] in titles and abstracts." (PMID 36918822, 2023). "According to several studies, NEDD4 acts as an oncoprotein that promotes cancer cell development." (PMID 36293239, 2022). "NEDD4 has shown to play a major role in chemoresistance in various cancers." (PMID 36293239, 2022).
cancer (continued). "Therefore, in malignancies, NEDD4 behaves as both an oncogene and a tumor suppressor, thus NEDD4 inhibitors or activators are needed for cancer treatments." (PMID 36293239, 2022). "The function of NEDD4 in cancer cell proliferation is demonstrated by several studies." (PMID 36293239, 2022). "The E3 ligase NEDD4-1 plays dual roles as an oncogene and tumor suppressor in cancers." (PMID 36552825, 2022). "Taken together, NEDD4 seems to prevent autophagy in cancer cells." (PMID 36293239, 2022). "Therefore, due to its role in tumorigenesis, NEDD4 can be a potential target in drug discovery against various types of cancer." (PMID 36293239, 2022). "In addition, we briefly explain the significance of NEDD4 as a possible target for cancer treatment." (PMID 36293239, 2022). "As a result, targeting NEDD4 could be an essential therapeutic approach for the management of human cancers." (PMID 36293239, 2022). "Taken together, NEDD4 increases cell migration and invasion in human cancer cells." (PMID 36293239, 2022). "NEDD4 is known to induce cancer cell survival in different cancers." (PMID 36293239, 2022). "Finally, a notable correlate to our finding that NEDD4 inhibits PFN1 function in NCCs are the contrasting roles of these proteins in cancer and neurodegeneration." (PMID 35440627, 2022). "This suggests that NEDD4 influences cell proliferation and cancer growth through Hippo signaling." (PMID 36293239, 2022). "NEDD4-1 overexpression induces apoptosis through the degradation of SAG in cancer cells." (PMID 36552825, 2022). "In addition, it was demonstrated that NEDD4 mainly acts as an oncogene in various cancers, but also plays a tumor-suppressive role in some cancers." (PMID 36293239, 2022). "In conclusion, NEDD4 has a crucial role in the survival of cancer cells." (PMID 36293239, 2022). "Moreover, NEDD4 promoted the ubiquitination of NEDD4/Rap2a, which eased the invasion and migration of U251 and U87 cancer cells." (PMID 36293239, 2022). "Previous studies have revealed that the role of NEDD4 in human cancers remains controversial." (PMID 33767993, 2021). "NEDD4 can elicit both oncogenic and tumor suppressor activities in human cancer cells." (PMID 33962630, 2021). "Second, the discrepant role of NEDD4 in human cancers is attributed to the dual regulation of PTEN, but the regulatory effect of NEDD4 on PTEN in HBV-associated HCC remains unclear." (PMID 33767993, 2021). "Based on the ambiguous function of NEDD4 in human cancers and our discrepant discovery in HBV-associated HCC, we speculated that NEDD4 might participate in favorable regulation during the process of hepatocarcinogenesis induced by HBV infection." (PMID 33767993, 2021). "Additionally, and in line with this notion, we identified three variants that bind more avidly to the SARS-CoV-2 S protein: two rare NEDD4 variants (I843R and R877G) and the N745S germinal variant in WWP1, which was already characterized in cancer studies." (PMID 33762578, 2021). "The HECT E3 ubiquitin ligase NEDD4 plays an important role in regulating cancer progression." (PMID 34833029, 2021). "Cancer stem cell-related and downregulated proteins by NEDD4 knockdown in MDA-MB-231." (PMID 33014839, 2020). "Cancer stem cell-related and upregulated proteins by NEDD4 knockdown in MDA-MB-231." (PMID 33014839, 2020). "Also, CKI/SCF (β-TRCP) signaling axis negatively regulates NEDD4 and can be targeted to rescue PTEN in human cancers mediated by NEDD4 overexpression." (PMID 32984016, 2020). "Moreover, many other cancer-related signaling pathways are also regulated by NEDD4, such as pAKT, IGF1R, and NOTCH pathways." (PMID 33014839, 2020). "Consistent with a previous report, NEDD4 staining was found in the cytoplasm of cancer cells." (PMID 31856858, 2019). "However, though p63 is a substrate of NEDD4, the importance of NEDD4 regulation of p63 in the context of cancer is overshadowed by the effects of NEDD4 regulation on its other substrates, most notably PTEN and c-Myc." (PMID 31905981, 2019).
cancer (continued). "Among E3s, neural precursor cell expressed developmentally downregulated 4-1 (NEDD4-1) has been shown to play a critical role in modulating the proliferation, migration, and invasion of cancer cells and the sensitivity of cancer cells to anticancer therapies via regulating multiple substrates." (PMID 31787758, 2019). "Early studies have shown that unconventional secretion of lysosomes is involved in cancer metastasis and cell migration and invasion, and NEDD4 participates in the ESCRT-dependent viral budding process, which resembles the MVB-dependent or the unconventional lysosomal secretion." (PMID 29455656, 2018). "Integrative analysis combining ChIP-seq and gene expression microarray data sets further revealed that these acetylation events at TSS are significantly correlated with the expression of their target genes, many of which are involved in cancer-related pathways, in a NEDD4-dependent manner." (PMID 28300060, 2017). "In other words, NEDD4 protein expression could possibly promote the carcinogenesis and cancer progression processes, such as PDAC cell proliferation, migration and invasion." (PMID 28423617, 2017). "This could explain why NEDD4 needs to be inhibited to sensitize cancer cells to anti-HER3 adjuvant therapy, whereas ITCH must be maintained to activate the drug biological effects, as we observed with the anti-HER3 antibody 9F7-F11." (PMID 27203743, 2016). "Furthermore, we and others have used therapeutic HER3 antibodies as probes to study the implication of HER3 inhibition/down-regulation using NEDD4 and Nrdp1 KD preclinical models of various human cancers." (PMID 25400118, 2014). "We therefore determined whether NEDD4-1-mediated SAG degradation would inhibit cancer cell growth and promote apoptosis." (PMID 25216516, 2014). "Our findings therefore demonstrate that NEDD4 may be a potential target in the treatment of human cancers." (PMID 24657926, 2014). "In addition, up-regulated HER3 expression by NEDD4 knockdown sensitized cancer cells for growth inhibition by an anti-HER3 antibody." (PMID 25400118, 2014). "Recently, lots of studies show that NEDD4-1 is involved in cancer development." (PMID 24340059, 2013). "However, whether this regulation among PHB2, SHIP2, and NEDD4 might be applicable to other types of cancer remains to be defined." (PMID 38200519, 2024). "Besides, some NEDD4 E3 ligase family genes might affect the prognosis regarding different cancer types to different extents such as WWP2 and Smurf2." (PMID 37291499, 2023). "NEDD4-1 exerts the dichotomous roles as an oncoprotein and a tumor suppressor in cancer cells." (PMID 36918822, 2023). "Targeting NEDD4 may be a promising strategy to activate or reactivate PTEN in cancer." (PMID 36774408, 2023). "However, how NEDD4 mediates the EGFR-dependent cancer cell migration remains elusive." (PMID 29455656, 2018). "However, it remains largely unknown how NEDD4 stability is regulated physiologically, and how it becomes aberrantly upregulated in human cancers." (PMID 24657926, 2014). "Hence, our findings suggest that targeting NEDD4 destruction could be a promising approach to achieve better treatment outcomes in human cancers." (PMID 24657926, 2014). "Therefore, we next explored whether β-TRCP1-mediated NEDD4 destruction is involved in cancer cell growth and migration." (PMID 24657926, 2014). "Therefore, targeted reduction of NEDD4 expression might be a promising strategy for treatment of these human cancers." (PMID 24657926, 2014). "However, further in-depth investigation is required to explore whether NEDD4 promotes cell invasion and metastasis in other human cancers, and its dependence on activation of the mTOR/Akt oncogenic signaling pathway." (PMID 24657926, 2014). "In breast and prostate cancer models, the knockdown of NEDD4 boosted HER3 expression, HER3 signaling, cell proliferation, and cancer progression." (PMID 38835349, 2024).
cancer (continued). "It has been demonstrated that NEDD4 and NEDD4L KO in IECs regulated Lgr5 degradation to mediate Wnt signaling and cancer development in APCmin mice." (PMID 39688910, 2024). "Further investigations revealed that vacuolar protein sorting 34 (VPS34) is the other target of NEDD4-1 in the autophagy machinery and plays an important role in the NEDD4-1-mediated ubiquitination of Beclin-1 in cancer cells." (PMID 36918822, 2023). "We selected representative proteins, NEDD4, APC/CCDH1, and FBXW7, which have been extensively studied in cancer metabolism and are also involved in the DDR pathway." (PMID 37176148, 2023). "However, whether NEDD4 regulates cancer metabolism remains poorly understood." (PMID 36923932, 2023). "NEDD4 is a particular E3 ligase for GCN2, which is activated in A549 cancer cells to increase tumor aggressiveness and survival for ubiquitination and degradation." (PMID 36293239, 2022). "More importantly, NEDD4 knockdown enhanced HER3 expression, making cancer cells sensitive to an anti-HER3 antibody which limited cell proliferation." (PMID 36293239, 2022). "In PCa, curcumin downregulates the NEDD4 protein and further upregulates PTEN and p73, and led to the suppression of cancer." (PMID 36293239, 2022). "The expression levels of both NEDD4 and KLF8 were elevated in cancer tissues relative to those in adjacent normal tissues." (PMID 35031788, 2022). "In several types of human cancer cell lines, PTEN degradation and increased NEDD4 levels have been discovered." (PMID 36293239, 2022). "More significantly, the NEDD4 knockdown increased HER3 expression, sensitizing cancer cells to the anti-HER3 antibody’s ability to suppress cell proliferation." (PMID 36293239, 2022). "It is likely that TRAF4 and Nedd4 differentially regulate IRS-1 and IRS-2 ubiquitination and subsequent IGF-1 signaling in cancer cells." (PMID 33991522, 2021). "On the other hand, the role of Neuronal precursor cell developmentally downregulated protein 4 (NEDD4) and its homologue NEDD4L in cancer is controversial." (PMID 31867777, 2020). "Depletion of Nedd4 limits the protein degradation of VDAC2/3, which increases the sensitivity of cancer cells to erastin." (PMID 31974380, 2020). "Thus, NC might be a promising agent for treating human cancers via inhibition of NEDD4." (PMID 33288736, 2020). "Thus, NEDD4 may be a promising target for new cancer therapy." (PMID 31856858, 2019). "These signalling pathways are often disrupted in human malignancies, and several NEDD4 family members, including NEDD4, NEDD4L, SMURF1, SMURF2, WWP1 and WWP2, also have altered expression or splicing in cancer." (PMID 31546607, 2019). "Low NEDD4–1 expression due to NEDD4–1 knockdown has been demonstrated to activate HER3 and increase cancer cell proliferation in vivo and in vitro." (PMID 30367623, 2018). "shRNA knockdown of NEDD4 elevated HER3 levels, resulting in increased HER3 signaling and cancer cell proliferation in vitro and in vivo in a MCF-7 mouse xenograft model." (PMID 25400118, 2014). "Mechanistically, we uncovered that PRL2 can post-translationally down-regulate PTEN, a tumor suppressor frequently inactivated in human cancers, by dephosphorylating PTEN at Tyr336, thereby promoting NEDD4-mediated PTEN ubiquitination and proteasomal degradation." (PMID 39665584, 2025). "We previously demonstrated that PRLs can post-translationally down-regulate PTEN, a tumor suppressor frequently inactivated in human cancers, by dephosphorylating PTEN at Tyr336, which promotes the NEDD4-mediated PTEN ubiquitination and proteasomal degradation." (PMID 39665584, 2025). "Consequently, NEDD4-1 is a compelling therapeutic target to restore PTEN stability and activity in cancers." (PMID 40002221, 2025). "In mechanism, the dual role of NEDD4-1 in cancer cells is ascribed to its non-selective ability to interact with the Proline-rich motifs that are universal regions in many proteins with different activities." (PMID 36918822, 2023).
cancer (continued). "Additionally, NEDD4 more efficiently recognizes a cancer-derived plasma membrane-philic mutant AKT (E17K) and regulates its trafficking into the nucleus, thus suggesting an oncogenic role of NEDD4 by AKT ubiquitination." (PMID 37176148, 2023). "Another study demonstrated a negative correlation between HER3, a key player in cancer, and NEDD4 levels." (PMID 36293239, 2022). "Although these results were completely opposite to those of previous studies using HBV-negative cell lines, they were not incomprehensible because the regulatory effect of NEDD4 in cancer remains elusive." (PMID 33767993, 2021). "The main functions of the NEDD4 gene were positive regulation of multiorganism process, regulation of cytoskeleton organization, and divalent inorganic cation homeostasis; the mainly enrichment pathways were MAPK signaling pathway and pathway in cancer." (PMID 34007304, 2020). "Neural precursor cell‐expressed developmentally downregulated gene 4‐1 (NEDD4‐1, also known as NEDD4) is a founding member of the NEDD4 family of E3 ligases and is involved in the proliferation, migration, invasion and drug sensitivity of cancer cells." (PMID 31390487, 2020). "The role of NEDD4 and NEDD4L in cancer progression has been controversial." (PMID 31867777, 2020). "Elevated NEDD4 levels and PTEN degradation are observed in various types of human cancer lines." (PMID 31856858, 2019). "In a group of carcinomas with low membranous HER3 expression, NEDD4–1 was negative in 38.5% (10 of 26) of carcinomas." (PMID 30367623, 2018). "To understand whether LATS1 stability is also regulated by other members of the NEDD4-like family of E3 ligases, we selected 4 ubiquitin ligases including NEDD4, WWP1, Smurf1 and Smurf2 that have been shown to be involved in the development of human cancers." (PMID 23573293, 2013). "However, NEDD4-1 has been reported to recognize and ubiquitinate diverse oncogenic substrates, including N-Myc, c-Myc and RAS proteins, exerts tumor-suppressive functions in cancers such as pancreatic cancer." (PMID 40809696, 2025). "The role of NEDD4 in oncogenesis is not yet fully clarified, and further investigation into DNA damage and cancer metabolism may lead to a greater focus on NEDD4 as a novel target for cancer therapy." (PMID 37176148, 2023). "NEDD4 has been reported as both tumour suppressor and oncogene, while the role of NEDD4L in cancer is largely unknown." (PMID 31867777, 2020). "Thus, targeting glucose/NEDD4-dependent H3 ubiquitination and subsequent transcription of IL1α/IL1β and GCLM may be an effective way to target cancers." (PMID 28300060, 2017). "Hence, targeting this newly identified signaling pathway, such as NEDD4, Gcn5 or their transcriptional targets including IL1α, IL1β and GCLM may be promising approaches for cancer therapy." (PMID 28300060, 2017). "Therefore, drugs that could induce NEDD4 degradation through upregulated expression or activating -TRCP1 or CKIδ, could be useful to treat human cancers with high expression of NEDD4." (PMID 24657926, 2014). "Interestingly, NEDD4-1 undergoes auto-ubiquitination that serves it as a scaffold for engaging the ubiquitin-specific protease 13 (USP13) to form a NEDD4-1/USP13 deubiquitination complex, which subsequently deubiquitinates and stabilizes VPS34 to induce phagophore nucleation in cancer cells." (PMID 36918822, 2023). "However, the expression of NEDD4 and its impact on cancer development in PDAC is not known." (PMID 28423617, 2017).